SLC25A20 (solute carrier family 25 member 20)
Diseases named in the same sentence as SLC25A20 in open-access papers (continued):
Sharing a sentence is not in itself a finding about the gene and the disease.
tumor (9 papers, 2020 to 2025). "Clinical significance study by Pearson’s correlation indicated that the expression of SLC25A20 was negatively associated with the tumor size and vascular invasion in patients with HCC." (PMID 33824298, 2021). "The molecular mechanism underlying the tumor-growth-suppressive function of SLC25A20 was further demonstrated to be mediated by the simultaneous induction of G1–S cell-cycle arrest and cell apoptosis." (PMID 33824298, 2021). "Given that hypoxia is common during tumor progression, we thus explored whether the down-regulation of SLC25A20 in HCC is associated with hypoxia." (PMID 33824298, 2021). "Here, we show that knocking down SLC25A20 in PDAC cells prevents HFD-dependent tumor growth in a xenograft model." (PMID 40521210, 2025). "The median survival time of KPC/Slc25a20+/- tumor-bearing mice was 3.1 weeks longer than that of KPC tumor-bearing mice." (PMID 40521210, 2025). "In the HFD group, SLC25A20 knockdown reduced tumor size by about 65% compared with the HFD control group." (PMID 40521210, 2025). "The protein-expression levels of SLC25A20 were commonly down-regulated in HCC tumor tissues compared with peritumor tissues." (PMID 33824298, 2021). "Expectedly, a significant overexpression of miR-132-3p and a negative correlation between the expressions of miR-132-3p and SLC25A20 (r = −0.493, p = 0.012) were observed in tumor tissues from patients with HCC." (PMID 33824298, 2021). "Finally, in the HFD group, SLC25A20 knockdown reduced tumor size by 95% compared with that in the HFD control group." (PMID 40521210, 2025). "Tumor growth in the SLC25A20 knockdown groups fed an NFD or HFD was almost the same." (PMID 40521210, 2025). "In addition, a more than 2-fold reduction in p-mTOR expression was shawn in the SLC25A20 knockdown tumor tissues." (PMID 40521210, 2025). "Immunohistochemical staining showed a significant increase of SLC25A20 expression in xenografts developed from SLC25A20 overexpression (SLC25A20) group compared with the empty vector (EV) group, suggesting that the tumor-suppressive effect was exerted by SLC25A20 overexpression." (PMID 33824298, 2021). "In addition to the significance of SLC25A20 on tumor growth, the biological function of SLC25A20 on HCC cell migration and invasion was also explored both in vitro and in vivo." (PMID 33824298, 2021). "SLC25A20 plays a critical tumor-suppressive role by inhibiting both growth and metastasis of HCC." (PMID 33824298, 2021). "In addition, a set of enzymes responsible for carnitine shuttling, which are encoded by SLC22A1, SLC25A20, SLC25A29, and CPT2, are downregulated in HCC tumor cells." (PMID 33424926, 2020). "Additionally, we found that the expression level of SLC25A20 was positively correlated with the maximum diameters of tumor, tumor-nodes-metastases (TNM) stage, and the incidence of portal vein tumor thrombosis (PVTT) of patients with HCC, implying a crucial role for SLC20A20 in HCC progression." (PMID 33824298, 2021). "To determine whether the protein-expression level of SLC25A20 is also decreased in HCC tissues, we performed immunohistochemical analysis to further analyze the expression of SLC25A20 in the paired tumor and the peritumor tissues from another 226 patients with HCC." (PMID 33824298, 2021). "In the KPC group, 7/13 mice formed large tumor masses, with destruction of parenchymal lobules in the pancreas, whereas only 2/12 mice in the KPC/Slc25a20+/- group formed large tumor masses." (PMID 40521210, 2025). "Tumor growth in the NFD and HFD SLC25A20 knockdown groups was quite similar, suggesting that HFD-induced tumor promotion is completely dependent on FAO." (PMID 40521210, 2025). "In particular, we found that carnitine and short-chain acylcarnitines were reduced in concentration in HB and that the carnitine metabolic pathway was dysregulated in the tumours (CPT1a, CPT2 and SLC25A20)." (PMID 37958356, 2023).
tumor (continued). "In the present study, we have shown that SLC25A20 expression is frequently decreased in HCC cell lines and tumor tissues mainly due to the up-regulation of miR-132-3p." (PMID 33824298, 2021). "Thus, the knockdown of SLC25A20 severely reduces the activity of mTOR due to a decrease in FAO-dependent ATP, and these changes are a major contributor to invasive tumor changes and reduced progression to PDAC." (PMID 40521210, 2025). "Altogether, SLC25A20 plays a critical tumor-suppressive role in carcinogenesis of HCC; SLC25A20 may serve as a novel prognostic factor and therapeutic target for patients with HCC." (PMID 33824298, 2021). "No significant change of the promoter methylation status of SLC25A20 was observed in primary tumor tissues when compared with normal liver tissues." (PMID 33824298, 2021). "However, no significant change of the promoter methylation status of SLC25A20 was observed in primary tumor tissues when compared with normal liver tissues." (PMID 33824298, 2021). "Consistently with this, a recent study using mass spectrometry (MS)-based proteomics analysis in tumor and adjacent non-tumor tissues from 159 patients with HCC has also revealed the down-regulation of SLC25A20 and its correlation with poor survival of patients with HCC10." (PMID 33824298, 2021).
metabolic disease (3 papers, 2020 to 2021). A congenital disorder (due to inherited enzyme abnormality) or acquired (due to failure of a metabolically important organ) disorder resulting from an abnormal metabolic process. "Previous studies had reported that mutations in SLC25A20 are closely associated with carnitine-acylcarnitine-translocase deficiency, resulting in a variety of metabolic diseases such as hypoglycemia, hepatic dysfunction, and muscle weakness." (PMID 33824298, 2021).
genetic disorder (1 paper, 2025). "A neonate was diagnosed with two genetic disorders due to a homozygous SLC25A20 variant and an MT-TL1 gene variation." (PMID 40129607, 2025). "Notably, one newborn was diagnosed with both a monogenic genetic disorder (SLC25A20 gene variation) and a mitochondrial disorder (m.3243A>G)." (PMID 40129607, 2025).
SLC25A20 also shares sentences with these, for which no sentence is quoted: very long chain acyl-CoA dehydrogenase deficiency (5 papers); Arrhythmia (4); maple syrup urine disease (4); bladder cancer (3); Hyperammonemia (3); methylmalonic acidemia (3); myocardial infarction (3); Obesity (3); Tyrosinemia type 1 (3); cardiac diseases (2); citrullinemia type I (2); glutaric aciduria (2); hypertrophic cardiomyopathy (2); MCAD deficiency (2); myopathies (2); propionic acidemia (2); prostate carcinoma (2); ankylosing spondylitis (1); aortic insufficiency (1); atherosclerosis (1); brain tumor (1); carnitine palmitoyltransferase deficiency (1); colon cancer (1); epimerase deficiency galactosemia (1); galactosemia (1); gallbladder cancer (1); gastric cancer (1); glioblastoma (1); HADH) deficiency (1); Hartnup disorder (1).
A further 22 diseases each share a sentence with SLC25A20 in 1 paper.